TRPV4 (transient receptor potential cation channel subfamily V member 4)
Diseases named in the same sentence as TRPV4 in open-access papers (continued):
Sharing a sentence is not in itself a finding about the gene and the disease.
colon cancer (continued). "Taken together, our results indicated that inhibition of TRPV4 expression contributed to apoptosis in colon cancer cells." (PMID 31189890, 2019). "In conclusion, inhibition of TRPV4 suppresses colon cancer development via activation of PTEN pathway." (PMID 31189890, 2019). "In conclusion, in this study we highlighted the functional importance of TRPV4 in mediating colon cancer development." (PMID 31189890, 2019). "To investigate the potential clinical role of TRPV4 in colon cancer, we first examined TRPV4 protein expression in cancer as well as in matched adjacent normal tissues from 18 human subjects." (PMID 31189890, 2019). "The notion of employing the downregulation of TRPV4 activity or expression as an approach to treat human colon cancer is worthy of further investigations." (PMID 31189890, 2019). "In this study, we showed that TRPV4 knockdown impaired the activation of AKT in colon cancer cells, consequently leading to inactivation of the mTOR and S6K pathway, and attenuated phosphorylation of 4E-BP1 and S6 ribosomal protein." (PMID 31189890, 2019). "Analysis of band densities revealed that in 78% (14/18) of colon cancer cases, TRPV4 expression was approximately eightfold higher when compared to normal tissues." (PMID 31189890, 2019). "Here, we demonstrated that TRPV4 affected colon cancer cell growth via regulation of the cell cycle progression from the G1 to the S phase." (PMID 31189890, 2019). "To investigate the pathophysiologic role of TRPV4 in colon cancer, we verified the expression and function of TRPV4 channels in colon cancer cell lines." (PMID 31189890, 2019). "Inhibition of TRPV4 suppressed colon cancer cell growth through arresting the cell cycle in the G1 phase and by inducing apoptotic as well as autophagic cell death." (PMID 31189890, 2019). "Taken together, these data indicated that PTEN participated in TRPV4-induced effects in colon cancer cell growth both through phosphatase-dependent and independent mechanisms." (PMID 31189890, 2019). "To provide direct evidence that TRPV4 channels are responsible for the tumorigenic ability of colon cancer cells, we subcutaneously injected HCT-116 or SW620 cells that were infected with shScramble or shTRPV4 into the right flank of nude mice." (PMID 31189890, 2019). "Knockdown of PTEN significantly abrogates TRPV4 silencing induced growth inhibition and recovers the capability of clonogenicity, as well as reduced apoptosis in colon cancer cells." (PMID 31189890, 2019). "This study represents the first study on TRPV4 in colon cancer and we aimed at elucidating the functional significance and molecular mechanism of TRPV4." (PMID 31189890, 2019). "To characterize the oncogenic mechanism of TRPV4 in colon cancer cell growth, we investigated the function of TRPV4 in cell cycle progression by flow cytometry." (PMID 31189890, 2019). "Apoptosis and autophagy induced by TRPV4 silencing attenuate cell survival and potentiate the anticancer efficacy of chemotherapeutics against colon cancer cells." (PMID 31189890, 2019). "In the mouse and human colon, TRPV4 is localized to the epithelial cells and unidentified cells of the submucosal and muscular layers, and has been reported in the human colon cancer cell line, Caco-2." (PMID 30365528, 2018). "Furthermore, TRPV4 is expressed in human colon epithelial cells and the Caco-2 human colon cancer cell line, and is increased in inflammatory bowel disease." (PMID 39338333, 2024). "Additionally, overexpression of TRPV4 has been shown to enhance the migration and invasion capabilities of colon cancer cells." (PMID 39517820, 2024). "We also showed previously that TRPV4 silencing induced colon cancer cell death through autophagy." (PMID 37707658, 2023). "Aberrant expression of TRPV4 is involved in diverse human cancers including colon cancer." (PMID 34814869, 2021).
colon cancer (continued). "Thus, our study indicates that TRPV4 can functionally regulate EMT, suggesting a novel link between TRPV4 and colon cancer aggressiveness." (PMID 34814869, 2021). "First, TRPV4 mRNA and protein expression have been evaluated in seven colon cancer cell lines." (PMID 31189890, 2019). "However, we found that TRPV4 silencing by siRNA enhanced apoptosis in human colon cancer cells and decreased resistance to chemotherapy-induced apoptosis." (PMID 31189890, 2019). "Furthermore, inhibition of TRPV4 suppressed the development of human colon cancer in vitro and in vivo through activation of PTEN signaling." (PMID 31189890, 2019). "In this study, we demonstrated that TRPV4 was upregualted in human colon cancer with poor outcome." (PMID 31189890, 2019). "Together, these data suggested an aberrant upregulation of TRPV4 in colon cancer." (PMID 31189890, 2019). "Together, these results indicated that the decreased cell growth induced by TRPV4 silencing may be attributed to inactivation of the ATK-mTOR pathway in colon cancer." (PMID 31189890, 2019). "In addition, silencing of TRPV4 potentiated the anticancer efficiency of 5-fluorouracil, oxaliplatin, and camptothecin against colon cancer cells." (PMID 31189890, 2019). "However, TRPV4 has not been previously shown to be involved in colon cancer invasiveness, and the underlying mechanism has not been reported." (PMID 34814869, 2021). "Thus, TRPV4 silencing-induced autophagy promotes colon cancer cell death." (PMID 31189890, 2019). "Consistent with this notion, we showed that inhibition of the activity or expression of TRPV4 in colon cancer cells may sufficiently disrupt Ca2+ homeostasis to increase the proportion of cells in the G1 phase and decrease the proportion of cells in the S phase." (PMID 31189890, 2019). "We next investigated whether TRPV4 plays a role in colon cancer cell growth." (PMID 31189890, 2019). "Next, we assessed TRPV4 expression by immunohistochemistry (IHC) using a tissue array consisting of 100 pairs of human colon cancer and matched nontumor colon tissues." (PMID 31189890, 2019). "Furthermore, the role of TRPV4 in colon cancer has not yet been identified." (PMID 31189890, 2019). "Therefore, we hypothesize that in colon cancer, abnormal expression of TRPV4 disrupted the negative regulation of AKT-mTOR signaling via sustained PTEN phosphorylation during tumor development." (PMID 31189890, 2019).
cystitis (11 papers, 2016 to 2024). Inflammation of the urinary bladder. "However, the resolution of inflammatory pain owing to the protective role of TRPV4 in cystitis-associated painful bladder hypersensitivity in vivo remains to be elucidated." (PMID 36618411, 2022). "Given that TRPV4 played an important role in CYP‐induced mouse cystitis 9, we, therefore, speculated that TRPV4 might be implicated in acrolein‐induce urothelial cell injury." (PMID 28244642, 2017). "Our results show the potential benefit of the intravesical administration the selective TRPV4 agonist GSK for painful bladder hypersensitivity in a rat model of LPS-induced cystitis." (PMID 36618411, 2022). "The results showed that the expression of TRPV4 was significantly increased in the epithelium of patients with severe ketamine cystitis." (PMID 34209184, 2021). "Chronic cystitis increased TRPA1 and TRPV4 transcripts in the (sub)urothelium of female rats, whereas in acute cystitis, TRPV1 and TRPV4 mRNA levels are decreased." (PMID 30087301, 2018). "Herein, we present our findings that CBX attenuated CYP‐induced cystitis in vivo and reduced acrolein‐elicited cell injury in vitro, possibly through mechanisms involving inhibition of TRPV4 channels and the channel‐mediated oxidative urothelial injury." (PMID 28244642, 2017). "CBX attenuated CYP‐induced cystitis in vivo and reduced acrolein‐induced cell injury in vitro, through mechanisms involving inhibition of TRPV4 channels and attenuation of the channel‐mediated oxidative stress." (PMID 28244642, 2017). "In a cyclophosphamide (CYP) model of cystitis, we found that the gene expression of several candidate MSCs (Trpv1, Trpv4, Piezo1, and Piezo2) were all upregulated in the urothelium and detrusor following chronic CYP-induced cystitis, but not acute CYP-induced cystitis." (PMID 35295484, 2021). "Together with UCs exfoliation during cystitis, the increased flushing activity mediated by TRPV4 may contribute to the elimination of the pathogen from the bladder lumen." (PMID 32435246, 2020). "In addition, antagonism of TRPV4 increased functional bladder capacity and reduced micturition frequency in mice and rats with acute cystitis, suggesting that chronic cystitis in human patients may improve with TRPV4 antagonist treatment." (PMID 30087301, 2018). "However, TRPV1 and TRPV4 protein levels are increased in acute and chronic cystitis." (PMID 30087301, 2018). "TRPV4-KO mice show impaired development of bladder pain and overactivity after CYP, despite obvious signs of severe cystitis." (PMID 36618411, 2022). "Therefore, we investigated the potential benefit of an intravesical TRPV4 agonist for painful bladder hypersensitivity in a rat model of LPS-induced cystitis and determined whether its effects modulate the LPS signal for inflammatory reaction, cytokine release, and macrophage phenotype change." (PMID 36618411, 2022). "Systemic administration of the selective and potent TRPV4 antagonist, HC-067047, decreased voiding frequency and increased bladder capacity in mice and rats following CYP-induced cystitis or repeated variate stress." (PMID 29321730, 2017). "Studies indicated that the intravesical administration of the TRPV4 antagonist HC067047 to block TRPV4 could ameliorate decreased bladder capacity and increased voiding frequency in both RVS and cyclophosphamide-induced cystitis animals." (PMID 33664402, 2021). "Induction of cystitis in the TRPV4 −/− mice (n = 4) (42 + cells, SD 2), however, did not result in any difference in c-fos expression when comparing them to controls (n = 4) (39 + cells, SD 2)." (PMID 27491796, 2016). "We found that several MSC genes including Trpv1, Trpv4, Piezo1, and Piezo2 were all upregulated in both layers of the bladder (urothelium and detrusor), following chronic CYP-induced cystitis, but not acute CYP-induced cystitis." (PMID 35295484, 2021).
pancreatitis (11 papers, 2011 to 2025). Inflammation of the pancreas. "Deletion of the TRPV4 gene inhibits the input to the spinal cord and the pain behavior associated with experimental pancreatitis due to caerulein." (PMID 21420431, 2011). "In addition to our findings in the pancreas, TRPV4 expression was found to be upregulated in a model of alcohol- and high-fat diet–induced pancreatitis, and TRPV4 is expressed in macrophages and linked with inflammation." (PMID 35451372, 2022). "TRPV4 is also likely to contribute to the pain associated with pancreatitis." (PMID 21420431, 2011). "Piezo1 is known to act together with other TRP channels: in response to pressure overload, Piezo1 transduces mechanical signals to TRPM4 channels in cardiac hypertrophy, and Piezo1 cooperates with TRPV4 channels in pressure-induced pancreatitis." (PMID 40019468, 2025). "An initial transient activation of Piezo1 by mechanical forces was shown to facilitate subsequent TRPV4 channel opening in pancreatic acinar cells with exaggeration of this mechanism leading to the pressure-induced pancreatitis." (PMID 38043795, 2023). "In a mouse model of pancreatitis due to pressure (by pancreatic duct obstruction), TRPV4-KO mice are significantly more protected." (PMID 33925979, 2021). "Other cation/calcium channels (e.g., Piezo) have been shown to have an effect on immune cells in a mechanosensitive manner and interestingly recent work demonstrates TRPV4 is required for Piezo1-induced pancreatitis." (PMID 32676078, 2020). "TRPV4 might be an important player in the development of PDAC from pancreatitis as it modulates Ca2+ mobilization in stellate cells and is up-regulated in pancreatic cancer tissues." (PMID 33925979, 2021). "However, the fact that TRPV4−/− mice developed the same degree of (acute) pancreatitis as wildtype mice argues against a role of TRPV4 channels in this disease." (PMID 27903970, 2017). "Moreover, Piezo1 and TRPV4 play a role in pressure-induced pancreatitis, which might act as a precursor lesion for PDAC." (PMID 40019468, 2025). "However, sustained elevation in intracellular calcium is necessary for pancreatitis, and this study demonstrates that Piezo1 activation triggers the opening of the TRPV4 channel, which leads to sustained elevation in intracellular calcium and the development of pancreatitis." (PMID 38379701, 2024). "In addition, TRPV4 may be a key mediator in paclitaxel chemotherapy-induced neuropathic pain, and in pancreatitis pain." (PMID 26043006, 2015). "We therefore decided to test it in a more specific preclinical pain model that relies on both, TRPV4 and TRPA1, in order to establish proof-of-principle that a dual-inhibitor can effectively treat pain and inflammation in pancreatitis." (PMID 27247148, 2016).
chronic obstructive pulmonary disease (10 papers, 2012 to 2023). A chronic and progressive lung disorder characterized by the loss of elasticity of the bronchial tree and the air sacs, destruction of the air sacs wall, thickening of the bronchial wall, and mucous accumulation in the bronchial tree. "It is important to underline that the precise role of TRPV4 channels in different types of cardiac arrhythmia and their potential as therapeutic targets is still an area of active investigation." (PMID 37371124, 2023). "TRPV4 dysfunction has already been associated to airway diseases: airway epithelial cells from cystic fibrosis patients show a defective regulation of TRPV4, and SNPs in the TRPV4 gene have been found to be associated with chronic obstructive pulmonary disease (COPD)." (PMID 22443337, 2012). "The chronic obstructive pulmonary disease (COPD)-predisposing variant P19S enhances the activity of MMP-1 by increasing TRPV4 activation." (PMID 33803491, 2021). "TRPV4, a calcium permeable cation selective channel, was found to be involved in chronic obstructive pulmonary disease (COPD) through releasing ATP and IL-1β." (PMID 35002766, 2021). "Together, these studies suggest that TRPV4 modulates ventricular electrical activity under basal conditions and may, thus, be involved in cardiac arrhythmias in aging or under pathological conditions (see Section 5 for details)." (PMID 37371124, 2023). "The same and other TRPV4 related SNPs were also found in patients with chronic obstructive pulmonary disease (COPD)." (PMID 33917551, 2021). "It has been proposed that inhibition of TRPV4 could have therapeutic benefits in several respiratory conditions, such as chronic heart failure, hypoxia-induced pulmonary hypertension, acute lung injury, chronic obstructive pulmonary disease and cough." (PMID 29100528, 2017).
depression (10 papers, 2013 to 2025). "Genome-wide association studies between control subjects and subjects with major depressive disorder revealed that TRPV4 mutations are a risk factor for depression." (PMID 39578735, 2024). "In addition, greater depression was associated with higher expression of IL-10 and TRPV4 using QIDS as the severity measure." (PMID 24143878, 2013). "Besides, LPS‐induced depression in mice is associated with increased TRPV4 in the hippocampus." (PMID 41399206, 2025). "Several studies indicate that TRPV1 and TRPV4 channel‐related neuroinflammation participates in anxiety and depression." (PMID 41399206, 2025). "It was demonstrated that the reduction in NSC numbers by TRPV4 activation was responsible for the induction of stress-induced depression in rodents." (PMID 39578735, 2024). "Taken together, these findings revealed that TRPV4 is the most suitable therapeutic target for stress-induced depression." (PMID 39578735, 2024). "Studies have revealed the use of TRPV4 antagonists can significantly reduce the occurrence of neuroinflammation in diseases such as Parkinson's disease or depression." (PMID 38334061, 2024). "TRPV4 rs3742037, TRPM8 rs17862920, TRPM8 rs10466942 and SLC17A8 rs11110359 were associated with migraine comorbidity depression risk." (PMID 37303955, 2023). "SLC17A8 rs11110359, TRPV4 rs3742037 and TRPM8 rs17862920 were associated with depression in dominant model (ORadj = 0.42, 95% CI = 0.20–0.84, p = 0.016; ORadj = 2.03, 95% CI = 1.06–3.96, p = 0.035; ORadj = 0.48, 95% CI = 0.23–0.96, p = 0.042, respectively)." (PMID 37303955, 2023). "Associations between SLC17A8, TRPV1, TRPV4 and TRPM8 gene polymorphisms and anxiety and depression in migraine patients." (PMID 37303955, 2023). "TRPV4 rs3742037, TRPM8 rs17862920 and SLC17A8 rs11110359 were associated with depression in dominant model [ORadj (95% CI): 2.03 (1.06–3.96), p = 0.035; 0.48 (0.23–0.96), p = 0.042; 0.42 (0.20–0.84), p = 0.016, respectively]." (PMID 37303955, 2023). "The TRPV4 inhibitor HC‐067047 or hippocampal Trpv4 knockdown alleviates depression‐like behaviors by reducing astrocyte and microglia activation, with suppressed CaMKII‐NLRP3 inflammasome expression and serum IL‐6, TNF‐α, and IL‐1β levels, and increased neurogenesis in the hippocampus." (PMID 41399206, 2025). "Of note, in the LPS-induced depression mouse model, the TRPV4 inhibitor HC067047 or TRPV4 shRNA could effectively rescue the abnormal behaviors by decreasing the expression of the NLRP3." (PMID 36552524, 2022). "Of the 9 ion channel receptors that we examined, P2RX7, TRPV1, and P2RY1 were upregulated in female patients during a depressive episode, and P2RY1 expression was positively related to depression severity along with 2 other ion channel receptors, TRPV4 and P2RX1." (PMID 24143878, 2013). "Thus, TRPV4 plays a key role in LPS‐induced depression‐like behaviors." (PMID 41399206, 2025). "A number of the selected hub genes in our study have been previously reported to be related to FMS or depression, including GRIK1&2, NGF, KCNQ2, GRIA1, TRPV4, IL1A, and GABAA receptors." (PMID 37065490, 2023). "Finally, two additional ion channel genes, P2RX1 and TRPV4, as well as two of the genes from our primary analysis, IL-10 and P2RY1, were related to depression severity as assessed by the QIDS and/or HRSD." (PMID 24143878, 2013). "Depression severity was related to increased IL-10, P2RY1, P2RX1, and TRPV4 expression." (PMID 24143878, 2013).